AGER (advanced glycosylation end-product specific receptor)
Diseases named in the same sentence as AGER in open-access papers (continued):
Sharing a sentence is not in itself a finding about the gene and the disease.
Insulin resistance (11 papers, 2016 to 2025). Increased resistance towards insulin, that is, diminished effectiveness of insulin in reducing blood glucose levels. "However, AGER-mediated development of metabolic inflammation—which predisposes to increased insulin resistance and type 2 diabetes mellitus—preferentially affects VAT." (PMID 38139276, 2023). "Our findings indirectly suggest that lncAGER-1 may induce inflammation mediated by AGER, therefore predisposing individuals to increased insulin resistance and T2DM." (PMID 38139276, 2023). "We found that obesity in women is associated with increased expression of AGER in subcutaneous adipose tissue, whereas AGER-mediated development of metabolic inflammation—which predisposes to increased insulin resistance and T2DM—preferentially affects the visceral depot." (PMID 38139276, 2023). "Ruelas and colleagues demonstrated lower expression levels of both the AGER gene and RAGE protein in PBMC derived from patients with prediabetes and insulin resistance than those in the PBMC-isolated from normal healthy volunteers." (PMID 35237235, 2022). "This happens via receptors that bind to advanced glycation end products, such as RAGE (advanced glycosylation end product-specific receptor), TLR4 and other receptors that regulate the activity of NFκB, constituting another link between diet and insulin resistance." (PMID 27437032, 2016). "Notably, we found that SAT, but not OAT AGER expression was a strong predictor of subjects’ homeostatic model assessment of insulin resistance (HOMA-IR)." (PMID 34103691, 2021). "Therefore, in the present work, we analyzed the gene expression of AGER (RAGE), RELA (NF-kB p65sub-unity), and NFE2L2 (NRF2) in PBMC of obese individuals with and without insulin resistance." (PMID 31231489, 2019).
asthma (10 papers, 2012 to 2024). "In a previous study, we have showed that HHIP, FAM13A1, AGER and RARB associated with pre-bronchodilator lung function in subjects with asthma." (PMID 30068317, 2018). "All the evidence indicates rs1980057 in HHIP, rs2869967 in FAM13A1, and rs2070600 in AGER are functionally relevant SNPs important for lung function in the general population and in subjects with COPD or asthma." (PMID 30068317, 2018).
diabetic nephropathy (10 papers, 2015 to 2025). "Previous studies observed that overexpression of miR-185-3p improved the renal function of diabetic nephropathy mice by inhibiting and reducing the expression of AGER." (PMID 36304901, 2022). "MiR-185-3p can downregulate AGER expression and improve renal function in diabetic kidney disease (DKD) mice." (PMID 36230932, 2022).
lung fibrosis (10 papers, 2015 to 2024). "We concluded that the AGER rs2070600 minor allele (Gly82Ser mutation) is associated with the pathogenesis of pulmonary fibrosis in CPFE in Japanese patients." (PMID 32732977, 2020). "In conclusion, the AGER rs2070600 SNP (Gly82Ser mutation) was associated with the pathogenesis of pulmonary fibrosis in CPFE in Japanese patients." (PMID 32732977, 2020). "AGER knockout mice also spontaneously develop features of lung fibrosis with late age and display an increase in DNA damage and senescence, which leads to an increased formation of lung carcinomas over time compared to wild-type animals." (PMID 37240472, 2023). "In comparison to the neutrophilic cases, the IPA analysis of the proteomic datasets derived from horses with metachromatic inflammation revealed enrichment in pathways related to hypersensitivity reaction (CD44, ICAM1, SOD1, PSAP, CDH1) and lung fibrosis (AGER, TGFBR2, FBLN1, S100A9)." (PMID 39594673, 2024). "Surprisingly, however, AGER knockout mice are protected from bleomycin-induced lung fibrosis." (PMID 37240472, 2023).
chronic kidney disease (8 papers, 2013 to 2025). Impairment of the renal function secondary to chronic kidney damage persisting for three or more months. "Moreover, AGER expression was found to be closely associated with the worsening of chronic kidney disease." (PMID 23894685, 2013).
diabetic retinopathy (8 papers, 2014 to 2024). "Finally, the AGER gene and the advanced glycosylation end-product-specific receptor were associated with diabetic retinopathy at both the transcriptomic and proteomic levels." (PMID 38791494, 2024). "Our AGER gene SNV analysis not only provides a deeper understanding of diabetic retinopathy pathogenesis, but also implies novel targets for DR gene therapy." (PMID 35099614, 2022). "Despite the comprehensive work and analysis done on finding the association between AGER gene SNV and DR risk, none of the identified polymorphisms have achieved widespread acceptance as a marker of high risk of diabetic retinopathy." (PMID 35099614, 2022).
heart failure (8 papers, 2018 to 2025). Inability of the heart to pump blood at an adequate rate to meet tissue metabolic requirements. "In addition, according to the findings of the PheWAS study, the utilization of AGER inhibitors may elevate the risk of nine diseases, including heart failure, non-small cell lung cancer, and adrenocortical insufficiency, among others." (PMID 38566994, 2024).
Hypertension (8 papers, 2014 to 2026). The presence of chronic increased pressure in the systemic arterial system. "Advanced glycation endproducts (AGEs), produced by the lack of glycemic control in diabetic patients,interact with their AGE receptors (AGER) resulting in increased arterialstiffness, inflammation and endothelial changes - which increases the risk ofdeveloping hypertension and other complications." (PMID 36300672, 2022).
metabolic syndrome (8 papers, 2012 to 2024). A cluster of metabolic risk factors for CARDIOVASCULAR DISEASES and TYPE 2 DIABETES MELLITUS. "Polymorphisms in the AGER gene, −374 T/A (rs1800624) and −429 T/C (rs1800625), have been associated with several metabolic conditions, but their role in metabolic syndrome (MS) has not been established." (PMID 37110179, 2023).
atrial fibrillation (7 papers, 2016 to 2025). A disorder characterized by an electrocardiographic finding of a supraventricular arrhythmia characterized by the replacement of consistent P waves by rapid oscillations or fibrillatory waves that vary in size, shape and timing and are accompanied by an irregular ventricular response. "Interindividual susceptibility likely varies by genetics: canonical atrial fibrillation loci (e.g., PITX2, ZFHX3) and variants in glycation pathway genes (e.g., AGER) may modify the association between acute–chronic glycemic mismatch and new-onset atrial fibrillation (NOAF)." (PMID 41040867, 2025). "Third, genetic variants (e.g., AGER polymorphisms) or interactions with atrial fibrillation-related genes (e.g., PITX2) were not explored." (PMID 40705819, 2025).
autoimmune disease (7 papers, 2017 to 2024). A disorder resulting from loss of function or tissue destruction of an organ or multiple organs, arising from humoral or cellular immune responses of the individual to their own tissue constituents. "AGER signaling pathway plays an important role in diverse physiological and pathophysiological processes and diseases such as autoimmune diseases and cancer." (PMID 35372081, 2022). "Plasma proteins with positive correlation with AS in this study were TNF, FKBPL, AGER, and ALDH5A1.TNF is a crucial cytokine playing a key role in the human immune response, involving various inflammatory and autoimmune diseases in their onset and development." (PMID 38566994, 2024).
glioma (7 papers, 2020 to 2025). A benign or malignant brain and spinal cord tumor that arises from glial cells (astrocytes, oligodendrocytes, ependymal cells). "More recently, the expression of AGER in tumour-associated microglia and macrophages has been shown to promote angiogenesis in glioma suggesting that targeting the interaction of AGER ligands with their receptors may have therapeutic potential." (PMID 36555253, 2022). "Our analysis of the human glioma TCGA database (Squatrito, 2015–2021) suggest a direct correlation between AGER (RAGE gene) and a number of lymphocyte markers in glioblastoma." (PMID 34975408, 2021).
Stroke (7 papers, 2013 to 2025). Sudden impairment of blood flow to a part of the brain due to occlusion or rupture of an artery to the brain. "Genetic mutations in both AGER and TGF-β receptors have been previously shown to increase the risk of various SCD complications, including stroke, priapism, infection, avascular necrosis, pulmonary hypertension, acute chest syndrome, and acute pain crises." (PMID 40141459, 2025).
type 1 diabetes (7 papers, 2015 to 2025). "This supports an association between the expression of AGER and its correlated genes and that of glucagon secretion in the islets from type 1 diabetes donors." (PMID 37558746, 2023). "The rs1800624 SNP involves AGER gene regulation and may be related to reduced risk of heart disease, cancer, Crohn's disease, and type 1 diabetes complications." (PMID 30863465, 2019). "Taken together, these results from microarray bioinformatics are consistent with an association between the expression of AGER, its ligands, signaling pathways and correlated genes and the expression of GCG in type 1 diabetes." (PMID 37558746, 2023). "Altogether, these data further support a role for AGER and its correlated genes in modulating biological pathways and cellular components with relevance to the secretion of glucagon in type 1 diabetes." (PMID 37558746, 2023). "In RNA microarray, RAGE (AGER) gene expression was the most important predictor of islet glucagon expression in type 1 diabetes." (PMID 37558746, 2023). "We utilized random forest ensemble machine learning to generate a model to explain the expression of GCG using AGER and its correlated genes in islets from donors with type 1 diabetes." (PMID 37558746, 2023). "We found that islets from type 1 diabetes donors had differential expression of the RAGE gene (AGER) and its correlated genes, based on glucagon expression." (PMID 37558746, 2023). "AGER and DRB1 variants seemed to work in synergy in activation of immune response and in involving diabetes type 1 complications." (PMID 30863465, 2019).
gastric cancer (6 papers, 2017 to 2024). A primary or metastatic malignant neoplasm involving the stomach. "Studies indicate that AGER is overexpressed in various types of malignant tumors, including esophageal and gastric cancers." (PMID 39409043, 2024).
rheumatoid arthritis (6 papers, 2007 to 2024). A chronic, systemic autoimmune disorder characterized by inflammation in the synovial membranes and articular surfaces. "The study for AGER G82S polymorphism introduced by rs2070600 on rheumatoid arthritis (RA), a representative autoimmune and inflammatory disease, showed that G82S showed the association with the risk of RA." (PMID 34782693, 2021).
amyloid (5 papers, 2013 to 2023). "SAA receptors, such as SELS (glucose homeostasis and ER stress), ABCA1, ABCA7, SCARB1 (cholesterol efflux), CD36, TLR2, TLR4, CST3 (inflammatory signaling), FPR2 (chemotaxis and immune cell activation), and AGER (amyloidosis), have been reported previously." (PMID 27799725, 2016).
colorectal cancer (5 papers, 2018 to 2025). A primary or metastatic malignant neoplasm that affects the colon or rectum. "AGER is a multi-ligand receptor that binds various ligands derived from a damaged cell and its up-regulation at both mRNA and protein level is associated with the majority of cancers including gastric, breast, hepatocellular, colorectal carcinoma." (PMID 31681566, 2019). "Functional studies have proven that lncAGER-1 acts as a miRNA sponge and indirectly modulates the expression of AGER in lung or colorectal cancer." (PMID 38139276, 2023).
lung adenocarcinoma (5 papers, 2017 to 2025). A carcinoma that arises from the lung and is characterized by the presence of malignant glandular epithelial cells. "In this study, we initially examined the correlation between AGER polymorphisms and disease susceptibility for lung adenocarcinoma in the Japanese population." (PMID 29212235, 2017). "Interestingly, recent analyses of TCGA data show that AGER (encoding RAGE) expression is significantly downregulated in lung adenocarcinoma compared to matched normal lung tissue, and that low RAGE expression correlates with poorer overall and disease-free survival." (PMID 41155277, 2025). "We hypothesized that the AGER polymorphisms aggravate tumor-associated systemic inflammatory conditions, as indicated by elevated NLRs, and therefore AGER polymorphism could predict survival in patients with lung adenocarcinoma, independently of the effect of EGFR mutations." (PMID 29212235, 2017). "The expression level of AGER was significantly reduced in lung adenocarcinoma (LUAD) and lung squamous cell carcinoma (LUSC)." (PMID 37497166, 2023). "However, AGER polymorphisms; rs2070600, rs1800624, and rs1800625, did not increase the risk of lung adenocarcinoma in the Japanese population." (PMID 29212235, 2017).
prostate carcinoma (5 papers, 2009 to 2020). A carcinoma that arises from epithelial cells of the prostate gland. "Additionally, previous bioinformatics analysis has indicated AGER contributed to prostate cancer cell proliferation by promoting Rb phosphorylation and degradation." (PMID 29298878, 2018).
Anxiety (4 papers, 2019 to 2025). Intense feelings of nervousness, tension, or panic often arise in response to interpersonal stresses. "Annotations between anxiety and the gene AGER, suggest that 129S1/SvImJ mutant of the Trpc5 gene in mice (allele Trpc5tm1.1Clph/Y, by Knockout), decreases anxiety in mouse." (PMID 40560842, 2025). "Knockout of the gene AGER in mice suggests a decrease in anxiety in mice." (PMID 40560842, 2025). "Regarding antioxidant properties of melatonin, Ergenc and co-workers examined melatonin effects on S100B, AGE receptor (AGER), and AGE levels, oxidative stress, and anxiety and depressive like-behaviors in streptozotocin-mediated diabetic rats." (PMID 32280378, 2020).
Arthritis (4 papers, 2016 to 2019). Inflammation of a joint. "Importantly, accumulating data suggests RAGE may play a role in a range of diseases including COPD, Alzheimer’s disease, arthritis and diabetes and so a greater understanding of AGER regulation by genetic mechanisms has broad implications." (PMID 27755550, 2016).
cervical cancer (4 papers, 2018 to 2025). A primary or metastatic malignant neoplasm involving the cervix. "AGER (advanced glycosylation end-product-specific receptor) was shown to be associated with increased cell migration in cervical cancer, but the opposite as per our analysis." (PMID 37895248, 2023). "The underlying mechanism responsible for the effects of AGER on the motility of cervical cancer cells remains to be further clarified." (PMID 29298878, 2018). "AGER is overexpressed in cervical cancer cell lines and can promote their proliferation and migration." (PMID 40901472, 2025). "Overexpression of AGER promotes and silencing its expression suppresses the proliferation and migration of cervical cancer cells." (PMID 29298878, 2018). "In this investigation, we reported, for the first time, that AGER was positively expressed in a panel of squamous cervical cancer cells." (PMID 29298878, 2018). "However, AGER is upregulated in cervical cancer, promoting proliferation and migration of cervical squamous cancer cells." (PMID 35494074, 2022). "Thus, AGER may be a newly recognized factor regulating cancer cell migration and metastasis in cervical cancer." (PMID 29298878, 2018). "Our current data provide novel evidence for a potential role of AGER in bridging HPV-induced inflammation and cervical cancer." (PMID 29298878, 2018).
multiple sclerosis (4 papers, 2022 to 2025). A progressive autoimmune disorder affecting the central nervous system resulting in demyelination. "Regarding the rs1800624 variant of AGER, while direct evidence linking it to major neurodegenerative diseases is limited, some studies suggest it may modulate risk for neuroinflammatory and neurodegenerative disorders such as optic neuritis—a condition often preceding multiple sclerosis." (PMID 40981102, 2025).
non-small cell lung carcinoma (4 papers, 2012 to 2024). A group of at least three distinct histological types of lung cancer, including non-small cell squamous cell carcinoma, adenocarcinoma, and large cell carcinoma. "Remarkably, AGER rs2070600 polymorphism, which increases ligand-binding affinity, is a potential prognostic factor in non-small cell lung cancer, but the underlying mechanism is unclear." (PMID 29212235, 2017). "The expression of lncRNA-LINC00173 is reduced in non-small cell lung cancer, causing miRNA-182 to aggregate and inhibit the Advanced Glycosylation End-Product Specific Receptor (AGER) / nuclear factor kappa-B (NF-κB) pathway, promoting tumor growth and metastasis." (PMID 32751923, 2020).
colon carcinoma (3 papers, 2015 to 2022). "Another study demonstrated that advanced glycosylation end product-specific receptor (AGER) is crucial for HMGB1-induced autophagy in pancreatic and colon cancer cells." (PMID 36230955, 2022).
thyroid cancer (3 papers, 2018 to 2023). "Lower expression of AGER was revealed in breast invasive carcinoma (BRCA), thyroid carcinoma (THCA), kidney chromophobe (KICH), LUAD, and LUSC compared with corresponding normal tissues." (PMID 37497166, 2023).
triple-negative breast carcinoma (3 papers, 2023 to 2025). An invasive breast carcinoma which is negative for expression of estrogen receptor (ER), progesterone receptor (PR), and human epidermal growth factor receptor 2 (HER2). "AGER promotes tumor progression and metastasis-related pathways, particularly in aggressive subtypes like triple-negative breast cancer, making it a candidate for risk stratification." (PMID 40647480, 2025).
acute pancreatitis (2 papers, 2019 to 2023). An acute inflammatory process that leads to necrosis of the pancreatic parenchyma. "We previously demonstrated that AGER contributes to AIM2 inflammasome activation by modulating dsRNA-dependent protein kinase phosphorylation in macrophages during acute pancreatitis." (PMID 31440260, 2019). "For example, the autophagy receptor protein sequestosome 1 (SQSTM1) increases advanced glycosylation end-product-specific receptor (AGER)-dependent ACSL4 expression, leading to PUFA production for autophagosome formation and subsequent ferroptosis, which promotes acute pancreatitis." (PMID 37372148, 2023).
carotid atherosclerosis (2 papers, 2015 to 2025). A thickening and loss of elasticity of the walls of carotid arteries that occur with formation of atherosclerotic plaques. "We assessed the expression of AGER isoform 1 that codes for the full-length AGER protein and its splice variant AGER isoform 6, encoding the truncated esAGER protein, in samples of carotid atherosclerosis removed from patients undergoing carotid endarterectomy." (PMID 26226616, 2015). "In this paper, we provide evidence for the association of the AGER SNP rs1035798:C>T with CV death and report differential expression of AGER isoforms within biopsies of carotid atherosclerosis." (PMID 26226616, 2015).